ALB (albumin)
Diseases named in the same sentence as ALB in open-access papers (continued):
Sharing a sentence is not in itself a finding about the gene and the disease.
malnutrition (continued). "In contrast to the majority of the few available studies investigating malnutrition in arthroplasty, biomarkers such as Albumin and Pre-Albumin were not quantified in our study." (PMID 29544497, 2018). "Albumin is a negative acute phase protein that decreases with inflammation and due to other reasons, such as malnutrition, increased age and disease." (PMID 30166572, 2018). "Animal below hypocaloric conditions did not present malnutrition, which had been corroborated in our laboratory by parameters such as albumin, hemoglobin concentration, and mean corpuscular hemoglobin (data not shown)." (PMID 28220106, 2017). "Serum albumin is also one of the negative acute-phase proteins as well as an indicator of previous malnutrition." (PMID 28938875, 2017). "Serum proteins that are considered as nutritional markers are albumin, prealbumin tranferrin, and retinol binding protein, but no serum protein has been found to be specific for malnutrition." (PMID 28114891, 2017). "Laboratory parameters such as hemoglobin, total protein, albumin, or total cholesterol were not sensitive enough to detect changes in nutritional status during the early stages of malnutrition." (PMID 28088190, 2017). "Serum albumin levels should not be relied on to define malnutrition but should remain a part of the nutritional status assessment in addition with the other indices." (PMID 28673364, 2017). "Albumin synthesis can be rate limited, yet this is only seen rarely in extreme malnutrition, which does not apply for our cohort since the BMI with a median of 25.0 (IQR 22.6-28.4) kg/m2 was normal." (PMID 29113384, 2017). "It has been noted that malnutrition in the absence of inflammation does not usually result in significant falls in serum albumin, probably because of compensatory reductions in albumin fractional catabolic rate and resting energy expenditure." (PMID 29026589, 2017). "Although serum protein and albumin were previously suggested as biomarkers for malnutrition, serum albumin is not well correlated to protein mass and does not always significantly increase following nutritional programmes." (PMID 28619005, 2017). "We did not directly measure any inflammatory markers; however, albumin is a recognized surrogate for inflammation and malnutrition." (PMID 28385153, 2017). "Because, serum albumin is the indicator of nutritional status, the malnutrition was deteriorated in patients without NK1 antagonist after TACE or HAIC." (PMID 29203965, 2017). "This increase in mortality was independent of malnutrition, a condition that until recently was thought to be the reason for reduced albumin levels." (PMID 26885251, 2016). "We note that the normal preoperative albumin levels observed do not suggest malnutrition, but also that albumin has a low sensitivity and specificity for clinical malnutrition and that many of our patients had lost weight." (PMID 27777753, 2016). "The evidence is weak for using serum albumin as a marker of malnutrition in non-inflammatory states such as starvation." (PMID 27174435, 2016). "We found that serum albumin, insulin and ferritin measures did not change as a result of the restricted diet, indicating that malnutrition was not induced." (PMID 27213441, 2016). "Last, but not least important, no blood chemistry data were available to calculate Kt/V or urea reduction rate and no CRP (C-reactive protein) or albumin level data were available to determine the status of inflammation or malnutrition, respectively." (PMID 27240348, 2016). "Since the association between the SUA <5.5 mg/dL and mortality in patients on dialysis may be a feature of malnutrition, we dissected this relationship according to the SGA, albumin level, and BMI." (PMID 27310949, 2016). "In our study, BMI and other common markers, such as albumin, failed to predict malnutrition as determined by BCM." (PMID 27347538, 2015).
malnutrition (continued). "First, as the definition of improvement of malnutrition is not unanimous, we defined it as serum albumin >35 g/L and gain of body weight >3 kg based on our experience." (PMID 26200619, 2015). "Low albumin and RBC count have been regarded as constant features of malnutrition." (PMID 26241963, 2015). "Two studies found C3 to correlate with albumin, and with one exception, C3 levels were lower in children with oedematous than non-oedematous malnutrition." (PMID 25153531, 2014). "In the present study, tinzaparin maintained the serum albumin level, indicating that no malnutrition was present." (PMID 25489602, 2014). "So-called negative APP were uniformly low in children with malnutrition and infection, including transferrin, α-2-HS-glycoprotein, pre-albumin, fibronectin, and α-2-macroglobulin." (PMID 25153531, 2014). "The importance of malnutrition markers stood out, and the average score on the MNA was lower in patients who died (14.3 ± 5.9 vs. 18.2 ± 5.4; p < .001), with a good correlation between this score and albumin levels at admission (rho = 0.5; p < .001)." (PMID 25464932, 2014). "We found that higher BMI and lower serum albumin are independent predictors for pneumonia in CAPD patients with DN, which suggests that these patients should pay attention to weight control but avoid malnutrition." (PMID 23585903, 2013). "None of the patients displayed malnutrition, defined as BMI < 20 and albumin < 3.5 g/dl, at any time point." (PMID 23295149, 2013). "The biochemical parameter of plasma albumin showed that 58.33% of the sample were classified as presenting mild malnutrition, while transferrin showed that 89.58% of the sample was normal." (PMID 23338736, 2012). "Nevertheless, albumin is not a good parameter for assessing malnutrition in critical patients because of its long half-life." (PMID 23016957, 2012). "Albumin was lower in the early AVF failure group but as it is affected by numerous factors other than nutrition intake it is not a useful marker for malnutrition." (PMID 22574168, 2012). "While serum albumin is widely used to indicate nutritional status it did not consistently predict malnutrition outcomes in HIV- women or HIV+ women with higher CD4." (PMID 22532840, 2012). "Predictors of early mortality included: older age (P = 0.006), major co-morbidity (P = 0.01), malnutrition (P = 0.001), elevated red cell distribution width (RDW, P<0.001) and serum alkaline phosphatase (P = 0.004), and reduced serum albumin (P = 0.01) and haemoglobin (P = 0.04)." (PMID 22276145, 2012). "Besides cancer-dependent malnutrition, significant decreases in PFAA concentrations and various indicators of nutritional status such as BMI and serum albumin levels are observed in cancer-independent cachexia." (PMID 21915291, 2011). "By contrast, the phase angle between resistance and reactance as measured by BIA is a marker of cell integrity and is useful to quantify malnutrition and may be superior to other markers such as BCM, BMI, serum, albumin, cholesterol, and so forth." (PMID 22567264, 2011). "However, our current results demonstrated that when albumin and PG-SGA global rating were assessed concurrently, the PG-SGA was a stronger predictor of LOS, and therefore more sensitive to detect malnutrition in gynecological cancer patients." (PMID 20497581, 2010). "Patients who were moderately or severely malnourished and with hypoalbuminemia developed more chemotherapy-induced toxicity overall when compared with patients without malnutrition (31 vs. 22; p = 0.02) and normal albumin (54 vs. 41; p = 0.04), respectively." (PMID 20170547, 2010). "Patients malnourished and with hypoalbuminemia developed more chemotherapy-induced toxicity overall when compared with those without malnutrition (31 vs 22; p = 0.02) and normal albumin (mean ranks, 62 vs 43; p = 0.002), respectively." (PMID 20170547, 2010).
malnutrition (continued). "Serum albumin levels are influenced by nutritional and nonnutritional factors and probably albumin is not the most accurate marker of malnutrition." (PMID 21188242, 2010). "We did not assess serum albumin levels as none of the subjects showed any clinical signs of malnutrition." (PMID 21829282, 2008). "Assays for albumin, prealbumin (or transthyretin), transferrin and retinol binding proteins can be used as biological markers for malnutrition in patients with no ongoing inflammatory condition (option)." (PMID 12915908, 2003). "Mean albumin increased from 4.38 to 4.49 g/dL at 24 weeks (p = 0.003), and prealbumin from 24.9 to 26.1 mg/dL (p = 0.047), despite the absence of overt protein-calorie malnutrition at baseline." (PMID 41901085, 2026). "Notably, reductions in visceral protein concentrations such as albumin are often driven by inflammation rather than true malnutrition, and it is well established that obesity can coexist with low muscle mass, a condition known as sarcopenic obesity." (PMID 40912688, 2026). "Therefore, low albumin more likely reflects inflammatory severity rather than true malnutrition in this context." (PMID 41010314, 2025). "Additionally, given malnutrition’s significant negative impact on patient recovery and prognosis, we measured nutritional parameters, including ALB and Hb, to comprehensively assess nutritional status." (PMID 40871652, 2025). "In addition, malnutrition has a significant impact on serum BUN and ALB levels." (PMID 40308642, 2025). "In particular, GNRI primarily relies on serum albumin levels and body weight, which may not accurately reflect malnutrition in patients with HF, given the increased fluid retention and oedema, and altered body composition." (PMID 40074368, 2025). "Individuals who start peritoneal dialysis with nephrotic-range proteinuria and significant urine output may have low serum albumin but have no other evidence of malnutrition." (PMID 40785303, 2025). "According to the results, decreased levels of albumin (<3 g/dL) and hemoglobin (<11 g/dL), elevated homocysteine, CRP, IL-6 (>7.5 pg/mL), and IP-10 (>250 pg/mL) may attract medical processionals’ attention when diagnosing malnutrition." (PMID 40094974, 2025). "When all the data of the two groups were compared, it was found that the arm and calf circumference measurements, lymphocyte counts, BMI values, albumin, and hemoglobin values of the group with NRS-2002 score 3 and above were statistically significantly lower than those without malnutrition risk." (PMID 40507738, 2025). "Importantly, although hypoalbuminemia is commonly used as a marker of malnutrition, in inflammatory states, the liver undergoes reprioritization of protein synthesis and preferentially produces inflammatory proteins rather than albumin." (PMID 39886055, 2025). "Furthermore, GNRI is a simple and efficient means of diagnosing malnutrition—only requiring height, weight, and albumin levels—and has the added benefit of not requiring a caregiver to be present." (PMID 40407919, 2025). "Although low albumin is commonly considered a marker of frailty, malnutrition, and worse post-fracture outcomes, it may not specifically predict recurrence." (PMID 41375797, 2025). "It is important to note that the CONUT score’s reliance on serum albumin (a negative acute-phase reactant) may reflect both malnutrition status and subclinical inflammation, complicating its interpretation." (PMID 41144640, 2025). "Both CRP and albumin contribute to the CAR increase in this study, this being representative of progressive right-heart failure with systemic congestion, intestinal impairment with malnutrition, and low-grade systemic inflammation described by the other studies." (PMID 40208300, 2025).
malnutrition (continued). "The findings revealed a lack of correspondence between the rate of malnutrition and albumin levels in the group classified as being at lower nutritional risk but with inflammatory status, suggesting a possible mismatch between clinical classification and biochemical markers." (PMID 40507142, 2025). "The nutrition-inflammation prognostic indices used to assess malnutrition are on the basis of lymphocyte count and cholesterol and albumin values only, for which clinical cutoff values are not established and associations with patient reports are poorly defined." (PMID 39802818, 2025). "During the inflammatory process, these proteins may be low due to inflammation rather than malnutrition, since the liver prioritizes the synthesis of acute phase proteins (CRPs), consequently reducing the synthesis of albumin and TTR." (PMID 39519615, 2024). "Consequently, nutritional guidelines all advise that albumin should not be a marker of malnutrition acutely." (PMID 39658522, 2024). "But its definition was based on body weight loss, lower BMI, low calorie intake, with a low albumin and high CRP levels, and such definition may not clarify the severity of malnutrition." (PMID 39702125, 2024). "Another limitation is that the study did not look at other potential factors such as serum albumin, body mass index, malnutrition, or inflammatory markers that could have influenced the result of survival." (PMID 39184771, 2024). "For instance, low serum albumin levels may indicate acute or chronic inflammation rather than malnutrition, leading to a potential misdiagnosis." (PMID 39125381, 2024). "Very few (4%) agreed that low albumin levels are not necessarily an indicator of malnutrition." (PMID 39223630, 2024). "Emerging evidence suggests that the significant decline in serum albumin levels in hip fracture patients might be attributed to inflammation, rather than pre-existing malnutrition." (PMID 39076765, 2024). "Compared to CONUT, PNI only includes two parameters of albumin and lymphocyte count but without cholesterol level, which may explain the lower prevalence of malnutrition assessed by PNI." (PMID 40143933, 2024). "Inflammatory cytokines such as TNF-α and IL-6 inhibit albumin synthesis, indicating that hypoalbuminemia in PD patients may be more attributable to systemic inflammation rather than malnutrition." (PMID 39281816, 2024). "According to the GPS value, which reflects both the inflammatory and nutritional status, calculated using ALB and CRP levels, we observed the same particularity in both groups that most patients (16/25 CR-NET patients and 39/60 CRC patients, respectively) had mild to moderate malnutrition." (PMID 39000088, 2024). "On the other hand, a decrease in albumin level does not necessarily indicate malnutrition." (PMID 39420871, 2024). "It has been reported that serum albumin concentration is not a useful marker for malnutrition." (PMID 39420871, 2024). "Consequently, there is an association between inflammation and serum albumin, but not between malnutrition and serum albumin." (PMID 39125410, 2024). "Dehydration, malnutrition and liver and kidney reserve can all be taken into account when evaluating B/A as a comprehensive body reserve, which may be more helpful in determining the severity of an illness than BUN or serum albumin." (PMID 38027791, 2023). "Second, some important parameters, such as biochemical indicators, like albumin, pre-albumin, and other clinical indicators that may potentially influence the prediction of malnutrition, were not presented." (PMID 36819703, 2023). "Studies have reported that low albumin concentration reflects cancer-induced malnutrition and may have a negative impact on prognosis." (PMID 37836573, 2023). "However, the use of albumin as a biomarker of malnutrition or body composition has not been without criticism." (PMID 36891188, 2023).
malnutrition (continued). "However, in some situations, such as patients with proteinuria, albumin is not a good index for malnutrition." (PMID 37513579, 2023). "In pediatric population the data is still scarce, possibly because of the lack of a homogeneous way to assess malnutrition (BMI, serum albumin, serum proteins, arm muscle area, arm fat area...), and considering the challenge of addressing nutritional needs in the different phases of childhood." (PMID 36875838, 2023). "However, we believe that incorporating total cholesterol levels into the CONUT score will facilitate the assessment of patients with mild malnutrition who do not present with decreased albumin levels." (PMID 36832250, 2023). "Low serum albumin levels may occur secondary to PLE, nephropathy, and malnutrition." (PMID 36937979, 2023). "On the other hand, the blood albumin level, which is commonly used an indicator of malnutrition, was unchanged whether malnutrition was present or not." (PMID 37964096, 2023). "Also, not surprisingly, albumin, a biomarker that, when downregulated, correlates with malnutrition, high inflammatory burden, and poor prognosis, was higher in the inflammatory group of our study." (PMID 38069288, 2023). "Total protein and albumin levels were normal in both groups, and there was no obvious malnutrition." (PMID 38143707, 2023). "Second, anthropometric characteristics (weight/height) were not recorded as possible indicators of malnutrition, which could alter basal albumin levels." (PMID 37240554, 2023). "For example, serum albumin is no longer among the criteria used to identify malnutrition." (PMID 37780557, 2023). "As albumin is also a negative acute phase reactant it may be more an indicator of inflammation rather than malnutrition directly as the inflammation is a contributor to the development of malnutrition." (PMID 35862384, 2022). "Indeed, pre-albumin is a controversial marker of malnutrition and nutritional risks both in COVID-19 and non-COVID-19 patients." (PMID 35276795, 2022). "Bearing in mind that lower albumin concentration was one of the best determinants for predicting CDI in our study, improvements in diagnosing and treating hospital malnutrition are needed, the effects of which could benefit both patients and healthcare providers." (PMID 35740191, 2022). "However, adjusting for SGA score, the normalized protein catabolic rate, serum phosphate, bicarbonate, and albumin, as indicators of malnutrition, did not materially attenuate the relationship between predialysis serum potassium level and death." (PMID 35072043, 2022). "The drop in serum protein, albumin and globulin and their ratio in the higher stocking density (HSD) was a clear image of compromised innate immunity which may be due to inhibition of protein synthesis, liver cell lesions, kidney dysfunction or malnutrition." (PMID 35701448, 2022). "The demographic characteristics of the patients with regard to outcome considering BMI, age, ASA score, malnutrition status, cardiovascular disease, smoking habit, preoperative serum albumin, creatinine clearance, and types of surgery were not different between survivors and non survivors." (PMID 35329082, 2022). "Nonetheless, albumin and weight alone are not enough to reveal malnutrition, since only the evaluation of lean and fat masses, for instance, could detect sarcopenic malnutrition." (PMID 35276799, 2022). "Albumin, prealbumin, total cholesterol, hemoglobin, and total protein could be useful in screening for malnutrition, but were not included in our study." (PMID 36501224, 2022). "Moreover, low levels of albumin generally signify malnutrition and can exert negative effects on survival outcomes among patients with CRC." (PMID 35664562, 2022). "Furthermore, hypoalbuminemia was considered a predictor of mortality in community-acquired pneumonia (CAP), which is not surprising considering that albumin is involved in inflammation and indicates malnutrition." (PMID 36412638, 2022).